CHD7 (chromodomain helicase DNA binding protein 7)
Diseases named in the same sentence as CHD7 in open-access papers (continued):
Sharing a sentence is not in itself a finding about the gene and the disease.
prostate carcinoma (2 papers, 2010 to 2023). A carcinoma that arises from epithelial cells of the prostate gland. "Biased towards African-specific drivers (63 versus 9 shared), many are novel to prostate cancer (18/63), including several putative therapeutic targets (CHD7, DPF3, POLR1B, SETD1B, UBTF, and VPS72)." (PMID 37444571, 2023). "Secondly, detection of the CHD7 CRA_e transcript in normal human liver total RNA, in addition to the DU145 prostate carcinoma cell line, is an indication that this alternative CHD7 transcript is also expressed in normal human tissues." (PMID 20925924, 2010). "To confirm, by Western blot analysis, whether the novel CHD7 CRA_e transcript is in fact translated into a 100 kDa protein, we sub-cloned its coding sequence into the bicistronic lentiviral pLV-EGFP expression vector and overexpressed CHD7 CRA_e isoform in the DU145 prostate carcinoma cell line." (PMID 20925924, 2010). "Expression of the CHD7 CRA_e transcript was detected in normal liver, in addition to the DU145 human prostate carcinoma cell line from which it was originally isolated." (PMID 20925924, 2010).
RASopathies (2 papers, 2024 to 2025). "Also, for CHD7, KMT2D, and Noonan/RASopathy genes, systematic chart review up to 10 y after initial ascertainment gave similar estimates of NDD frequency as obtained by questionnaire at ascertainment." (PMID 40127276, 2025).
scoliosis (2 papers, 2012 to 2020). A congenital or acquired spinal deformity characterized by lateral curvature of the spine. "In this study, we aimed to estimate the relationship between the CHD7 gene with both susceptibility and the clinical form of scoliosis." (PMID 31924193, 2020). "Chd7 has been implicated in spinal deformities and scoliosis is one of the minor clinical features in some CHARGE patients." (PMID 22363697, 2012). "Previous findings indicate that approximately 60% of children with a CHD7 gene mutation, causing CHARGE, develop scoliosis in early childhood." (PMID 31924193, 2020). "The chd7 morphants did not exhibit any skeletal defects reminiscent of a scoliotic adult phenotype, however, suggesting that either scoliosis in CHARGE patients is secondary to the effects of attenuated Chd7 levels, or due to primary effects that occur later in development." (PMID 22363697, 2012).
acute lymphoblastic leukemia (1 paper, 2016). Leukemia with an acute onset, characterized by the presence of lymphoblasts in the bone marrow and the peripheral blood. "For the interaction partner of FAM124B, CHD8, one study so far described an oncogenic role in a mouse model for BCR-ABL1+ acute lymphoblastic leukemia, while neither the role of FAM124B nor its interaction with CHD7/8 have been described so far in AML." (PMID 27585840, 2016).
behavioral disorders (1 paper, 2023). "Moreover, we found that chd7 KO leads to morphological and behavioral disorders." (PMID 37686337, 2023).
bladder cancer (1 paper, 2017). "Among 31 tumor types, bladder cancer exhibited the most frequent CHD7 mutations (13 of 130 sequenced tumor samples, 10%)." (PMID 28649742, 2017).
blepharoconjunctivitis (1 paper, 2014). Inflammation of both the eyelids and the conjunctiva. "Eye irritation and probable blepharoconjunctivitis were observed in 11 of 16 Chd7+/Looper mice examined." (PMID 24840056, 2014).
campomelic dysplasia (1 paper, 2024). "Potentially pathogenic variants were discovered in the FAS and pFAS groups, including those known to cause craniofacial malformations, such as SOX9 (Campomelic Dysplasia), STRA6 (Matthew–Wood), CHD7 (CHARGE), MID1 and MED15 (Opitz–Kaveggia syndrome), and several 22q11.2DS genes." (PMID 38785976, 2024).
chronic otitis media (1 paper, 2012). Chronic form of otitis media (disease). "In this study, we report a mouse model with a spontaneous deletion mutation in the Chd7 gene and with chronic otitis media of early onset age accompanied by hearing loss." (PMID 22539951, 2012).
Coffin-Lowry syndrome (1 paper, 2022). A rare X-linked syndromic intellectual disability characterized by global development delay, postnatal growth retardation leading to short stature, facial dysmorphism, short hands with tapering fingers and progressive skeletal abnormalities including kyphoscoliosis and pectus carinatum/excavatum. "Briefly, a case diagnosed as Coffin-Lowry syndrome (disruption of CHD7) has normal CMA results but an abnormal karyotype result." (PMID 36636555, 2022).
colon cancer (1 paper, 2010). "Before the full-length structure of this gene was resolved, it had been described that the protein encoded by KIAA1416, a partial CHD7 transcript, is a colon tumor antigen, which is overexpressed in colon cancer cells." (PMID 20925924, 2010).
congenital malformations (1 paper, 2021). "The CHD7- and FGFR1-positive patient group was significantly enriched by additional non-reproductive congenital malformations." (PMID 34198905, 2021).
demyelination (1 paper, 2021). "Normally, in adult mice, Chd7 expression in the whitematter of the spinal cord is practically undetectable; however,lysolecithin-induced demyelination causes local re-expressionof Chd7 against the background of myelin regeneration viaOPC recruitment." (PMID 34595379, 2021).
depression (1 paper, 2022). "These genes include CHD7, ADCY3, ANK3, NWD1, CNTNAP2 and TSNAX-DISC1, each of which has been carefully considered and contrasted as no previous link between neural disorders or psychiatric conditions, including depression, has been made for risk preference." (PMID 34696705, 2022).
dry eye (1 paper, 2014). "Other Chd7 mutant mice have been reported to display keratoconjunctivitis sicca or “dry eye”." (PMID 24840056, 2014).
Duane syndrome (1 paper, 2010). "Recent reports have suggested that CPA6 may not be the sole causative Duane syndrome gene on chromosome 8, but the duplication of another more centromeric gene, CHD7, may be involved." (PMID 20885977, 2010).
endothelial dysfunction (1 paper, 2017). In vascular diseases, endothelial dysfunction is a systemic pathological state of the endothelium (the inner lining of blood vessels) and can be broadly defined as an imbalance between vasodilating and vasoconstricting substances produced by (or acting on) the endothelium. "CHD7 seems to be an acute marker of endothelial dysfunction, which explains the increase in de novo albuminuria and the recovery in sustained albuminuria." (PMID 28152519, 2017). "The hereby presented results support a potential involvement of kalirin and CHD7 proteins in human blood vessel endothelial dysfunction and show an increased expression of both by circulating EVs in albuminuric patients." (PMID 28152519, 2017). "Hence, we propose protein levels of kalirin and CHD7 in circulating EVs as novel endothelial dysfunction markers to monitor vascular condition in hypertensive patients with albuminuria." (PMID 28152519, 2017). "Thus, we propose protein levels of kalirin and CHD7 in circulating EVs as novel endothelial dysfunction markers in hypertensive patients with albuminuria." (PMID 28152519, 2017).
eye inflammation (1 paper, 2014). "An exact cause of the eye inflammation and discharge in Chd7 mutant mice is yet to be identified." (PMID 24840056, 2014).
hydronephrosis (1 paper, 2024). Collection of urine in the renal pelvis that results in dilatation of the renal pelvis and calyces. "Some of the CAKUT cases with associated malformations did reveal a pathogenic variant in WES (unilateral renal agenesis Hypomethylation C2; horseshoe kidney KMT2A; hydronephrosis FREM2, KANSL1; LUTO CHD7; renal hypoplasia GREBIL, POGZ)." (PMID 37535131, 2024).
Infertility (1 paper, 2017). "Our RNA profiling data strongly support the theory that in the high infertility risk group of cryptorchid boys insufficient PROK2/CHD7/FGFR1/SPRY4 gene expression, together with observed deficient EGR4 and PITX1 signaling, induce deficient LH secretion, which results in impaired mini-puberty." (PMID 29163975, 2017).
leukemia (1 paper, 2008). A malignant (clonal) hematologic disorder, involving hematopoietic stem cells and characterized by the presence of primitive or atypical myeloid or lymphoid cells in the bone marrow and the blood. "Our findings also suggest a possible role for CHD7 in cancer through the recruitment of MLL fusion proteins, which have been implicated in several forms of leukemia." (PMID 18846226, 2008).
Neurodegeneration (1 paper, 2023). Progressive loss of neural cells and tissue. "Interestingly, in advanced stages of cerebellar neurodegeneration, the expression of Rbfox1, Zfp521, and Chd7 host mRNAs was substantially decreased, in contrast to the surplus of the circRNA forms." (PMID 37019475, 2023).
osteoporosis (1 paper, 2022). A condition of reduced bone mass, with decreased cortical thickness and a decrease in the number and size of the trabeculae of cancellous bone (but normal chemical composition), resulting in increased fracture incidence. "Our research provided evidence that CHD7 regulates stem cell differentiation and cell fate decisions and revealed the functional association between histone modification and osteoporosis, which might shed light on therapeutic strategies for bone pathological disorders." (PMID 35418650, 2022).
otitis media (1 paper, 2012). Inflammation of the anatomical structures of the middle ear, which is most often caused by an infectious process. "Combining the results of histological and electrophysiological study, we conclude that hearing loss in the Chd7 mutant mice is primarily caused by otitis media." (PMID 22539951, 2012). "However, due to a premature stop codon in the mutant transcript, the CHD7 protein level in heterozygous mice is predicted to be half that of the +/+ mice, and this haploinsufficiency of Chd7 would lead to otitis media and other phenotypes." (PMID 22539951, 2012).
otitis media with effusion (1 paper, 2012). Otitis media associated with accumulation of fluid in the middle ear. "In our study of Chd7-deficient mice, we found that abnormal Eustachian tube structure and function, dysregulated epithelial proliferation and decreased middle ear cilia density rendered these mice susceptible to otitis media with effusion." (PMID 22539951, 2012).
ovarian carcinoma (1 paper, 2017). A malignant neoplasm originating from the surface ovarian epithelium. "CHD7 was highly amplified in more than 5% of samples among 11 tumor types, including breast, lung, colorectal, and ovarian cancers." (PMID 28649742, 2017). "Among 32 tumor types, CHD7 was more frequently (> 50%) amplified/gained in 11 tumor types, including breast, lung, colorectal, and ovarian cancers, and CHD6 was more frequently (> 50%) amplified/gained in eight TCGA tumor types, whereas CHD3 was more frequently deleted (> 50%) in nine tumor types." (PMID 28649742, 2017).
Primary amenorrhea (1 paper, 2016). "A hemizygous c.230_231insA mutation in SRY was identified in a female patient with 46,XY complete gonadal dysgenesis (DSD01), and a heterozygous c.7389delA mutation in CHD7 was found in a woman with a small uterus, primary amenorrhea, short stature, and dysplastic ears (DSD04)." (PMID 26980296, 2016).
schizophrenia (1 paper, 2019). A major psychotic disorder characterized by abnormalities in the perception or expression of reality. "For example, ITIH4 is associated with schizophrenia and CHD7 is implicated in autism." (PMID 31784694, 2019).
Snijders Blok-Campeau syndrome (1 paper, 2023). Snijders Blok-Campeau syndrome (SNIBCPS) is an autosomal dominant neurodevelopmental disorder characterized by global developmental delay with impaired intellectual development and delayed speech acquisition. "Pathogenic variants in CHD proteins contribute to the development of a range of neurological disorders, such as CHD1 in Pilarowski-Bjornsson syndrome, CHD3 in Snijders Blok-Campeau syndrome (SNIBCPS), CHD4 in Sifram-Hitz-Weiss syndrome, CHD7 and CHD8 in Autism Spectrum Disorder (ASD)." (PMID 36647159, 2023).
stomach adenocarcinoma (1 paper, 2022). "CHD5 was frequently mutated in stomach adenocarcinoma (7%) and UCEC (14%), whereas CHD7 mutations were identified in 8% of CRC cases." (PMID 35789070, 2022).
Stroke (1 paper, 2016). Sudden impairment of blood flow to a part of the brain due to occlusion or rupture of an artery to the brain. "Investigations of CHD7 function in gliogenesis at different developmental stages and in other neural diseases, such as stroke and spinal cord injury, that are associated with regenerative neurogenesis remain for future study." (PMID 27955690, 2016).
triple-negative breast carcinoma (1 paper, 2025). An invasive breast carcinoma which is negative for expression of estrogen receptor (ER), progesterone receptor (PR), and human epidermal growth factor receptor 2 (HER2). "This association may support the findings from CHD7 knockdown models in triple-negative breast cancer cell lines showing inhibition of cell proliferation and decreased gene expression of several CHD7 targets, including the NRAS oncogene." (PMID 41278204, 2025).
virus infection (1 paper, 2016). "Little is known about the role of CHD7/Kismet in the context of virus infection." (PMID 27827425, 2016).
tumor (33 papers, 2010 to 2025). "In CRC, CHD7 was amplified in 331 cases (53.7%), mutated with a frequency of 8%, identified with four gene fusion events, and more overexpressed in tumour tissues than in the adjacent normal tissues." (PMID 35789070, 2022). "In silico analysis of 32 tumor types revealed that CHD7 is the most commonly gained/amplified and mutated gene among the CHD members." (PMID 30850678, 2019). "In TCGA samples, 236 sequenced tumor samples contained a total of 291 CHD7 mutations: 250 missense, two in‐frame insertions, 37 truncating, and two other mutations." (PMID 28649742, 2017). "Among the 48 primary tumor samples, ASNS, CD40, CHD7, and ITPKB mutations were exclusively identified (n = 1 each; p = 0.0147) and were absent in the 67 metastatic samples." (PMID 40361470, 2025). "Using Tumor Immune Estimation Resource (TIMER) data, we found patients with CREBBP, EP300, CHD7 mutations and PRDM9 amplifications associated with low B‐cell infiltration, potentially aiding tumor growth." (PMID 40693457, 2025). "The knockdown of CHD7 expression in the xenograft was confirmed by immunofluorescent staining of CHD7 in frozen sections of the tumours from mice." (PMID 35789070, 2022). "The results indicated that the growth of tumours was significantly inhibited in athymic mice that had received tumours with CHD7 knockdown, as the tumour volume and weight were evidently inhibited in CHD7‐depleted groups." (PMID 35789070, 2022). "This is due to increased cancer cell proliferation and higher tumor growth rate, consistent with CHD7/BMI1 cooperation in regulating ERK1/2-induced MB proliferation." (PMID 33869187, 2021). "More recently, it has been shown that USP36 enhances CHD7 protein stability by direct deubiquitination, subsequently facilitating tumor progression." (PMID 33237263, 2020). "We show that cells displaying high level of CHD7 protein are found within the tumor mass in the three different samples analyzed." (PMID 30850678, 2019). "We further investigated the role of CHD7 in modulating tumor cell invasion using the Matrigel invasion assay." (PMID 30850678, 2019). "Public microarray database analyses revealed that CHD7 is up-regulated in tumor samples, when compared to normal brain tissue (NBT), even though no significant alteration in genetic copy number was detected." (PMID 30850678, 2019). "We show increased proliferation of G4 MB cells upon CHD7 silencing in vitro as well as increased tumor volume upon orthotopic xenografting of these cells into NOD/SCID mice, an effect that is dependent on BMI1 expression." (PMID 29212025, 2017). "In 7978 sequenced TCGA tumor samples, four CHD genes—CHD4, CHD5, CHD6, and CHD7—exhibited mutations in more than 200 tumor samples." (PMID 28649742, 2017). "Additionally, we examined the potential roles of ASCL1 and CHD7 in tumor progression by comparing their expression levels in squamous cell carcinoma tumors versus adjacent non-cancerous tissues." (PMID 40332288, 2025). "Moreover, the malignancy of the tumour with CHD7 knockdown was much lower than that of tumours formed by control RKO cells as indicated by Ki‐67 staining." (PMID 35789070, 2022). "Additionally, CHD7 KO impairs tumor growth and increases overall survival in an orthotopic mouse xenograft model." (PMID 30850678, 2019). "Immunohistochemistry of brain sections showed that cells displaying high protein levels are located at the border of the tumor suggesting a correlation between the levels of ectopic CHD7 overexpression and the migration and invasion phenotypes of LN-428 cells in vivo." (PMID 30850678, 2019). "Additionally, in SCLC, downregulation of CHD7 expression may weaken its inhibitory effect on cell proliferation, thereby promoting tumor growth and metastasis." (PMID 40332288, 2025). "We correlated epiRG scores with six major immune cell types and observed certain epiRG scores (CHD7‐mut, CREBBP‐mut, EP300‐mut) positively correlated with tumor proliferation." (PMID 40693457, 2025).
tumor (continued). "To further analyse the effect of CHD7 knockdown on the development of CRC in vivo, we constructed a mouse tumour‐bearing model, which can stimulate the growth of tumour in vivo." (PMID 35789070, 2022). "Mechanistically, CHD7 depletion sensitized PDAC cells to gemcitabine by triggering DNA damage and delayed tumor xenograft growth." (PMID 31769422, 2019). "Moreover, low CHD7 expression in the G4 meduloblastoma subtype, in combination with BMI1 overexpression, has recently been shown to contribute to tumor formation." (PMID 30850678, 2019). "Furthermore, we used CHD7‐depleted RKO and HCT116 cells to perform colony formation experiments on soft agar, which can detect the ability of tumour cells to form colonies in a non‐adherent state and reflect the malignant proliferation ability of tumour cells." (PMID 35789070, 2022). "Based on the literature, LOXL3, CHD7 and PDE3A could regulate the malignant behaviour of tumours." (PMID 36324258, 2022). "Additionally, using the CD133 cell surface marker, we observed that CHD7 is more expressed in the CD133 negative cell population in a subgroup of tumor samples." (PMID 30850678, 2019). "Silencing of CHD7 did not affect intraparenchymal invasion, while silencing of BMI1 alone significantly hampered tumor cell invasion, in keeping with previous reports." (PMID 29212025, 2017).